ANGPT2 (angiopoietin 2)
Diseases named in the same sentence as ANGPT2 in open-access papers (continued):
Sharing a sentence is not in itself a finding about the gene and the disease.
endothelial dysfunction (continued). "Moreover, emerging biomarkers such as copeptin, CXCL9, angiopoietin-2, and vitamin D have been investigated for their role in endothelial dysfunction, immune dysregulation, and clinical severity." (PMID 40430232, 2025). "Finally, VWF and ANGPT2 plasma levels are used as markers for endothelial dysfunction in inflammatory disorders." (PMID 40894883, 2025). "To ease clinical identification of these AKI sub-phenotypes, we developed and validated a 3-variable model that included plasma markers of endothelial dysfunction (angiopoietin-1 (Ang-1) and angiopoietin-2 (Ang-2)) and inflammation (soluble tumor necrosis factor receptor-1 (sTNFR-1))." (PMID 39695715, 2024). "In a case-control study in patients with type 2 diabetes, elevated plasma levels of chemokine ligand-16 (CXCL-16), angiopoietin-2, and TGF-β1, which are systemic biomarkers of inflammation, fibrosis and endothelial dysfunction, are independently associated with the development of microalbuminuria." (PMID 38542060, 2024). "In response to SARS-CoV-2 infection, ANGPT2 may be upregulated, leading to increased vascular permeability and subsequent endothelial dysfunction." (PMID 37239234, 2023). "Angiopoietin-2 and TMB have been associated with endothelial dysfunction and capillary leak." (PMID 35665340, 2022). "In addition, eGC stiffness was correlated with PCS concentrations (r = 0.35, p = 0.05) and cortex stiffness was positively correlated with Angpt-2 (Angiopoietin-2), a marker for endothelial dysfunction (r = 0.82, p < 0.01)." (PMID 36142571, 2022). "Besides, Angiopoietin-2 several other endothelial dysfunction markers, like PAI-1, ADAMTS3, d-dimer, sPECAM-1, TF and TM were found to correlate with viral load, but only in CCHF patients." (PMID 31357521, 2019). "The potential of angiopoietin-2 as a biomarker for endothelial dysfunction and unfavorable outcome has been extensively investigated in septic populations, but has been restricted to in vitro models or the evaluation of plasma markers in cardiac surgery patients." (PMID 30975180, 2019). "Both angiopoietin-2 and sFlt-1 may be considered markers of endothelial dysfunction in acute states." (PMID 28368336, 2017). "The biomarkers were representative of several biologic processes: apoptosis (soluble Fas), inflammation (soluble tumor necrosis factor receptor 1, interleukin 6, interleukin 8) and endothelial dysfunction, (angiopoietin 1, angiopoietin 2, and soluble vascular cell adhesion molecule 1)." (PMID 28814331, 2017). "Furthermore, we demonstrate that CFHb is independently associated with angiopoietin-2 and OPG, and that OPG is associated with endothelial cell adhesion molecules and microvascular and endothelial dysfunction, as well as with clinical biomarkers of severity, including lactate and AKI." (PMID 29872039, 2018). "Higher MYBPC3 was most prognostic in HFrEF while higher ANGPT2 and IGFBP7 (endothelial dysfunction and oxidative stress) in HFpEF." (PMID 41711204, 2026). "We further investigated ANGPT2 and VWF, two important endothelial dysfunction markers in multiple inflammatory disorders." (PMID 40894883, 2025). "Increased levels of ICAM-1, VEGF, and Angiopoietin-2 were found in corticosteroid resistant ITP patients compared with healthy controls, indicating the occurrence of endothelial dysfunction in ITP." (PMID 34326842, 2021). "Compared with the normal control, plasma ANGPT2 level in AAD patients were significantly elevated which indicated that inflammation, oxidative stress, and endothelial dysfunction might be involved in the pathogenesis of AAD." (PMID 35004874, 2021). "Moreover, a higher angiopoietin-2/angiopoietin-1 balance, indicating endothelial activation, at pre-LD was identified in patients subsequently developing ICANS, suggesting endothelial dysfunction prior to CAR T-cell therapy could influence the occurrence of toxicity." (PMID 38001703, 2023).
endothelial dysfunction (continued). "Established vascular markers like angiopoietin-2 and VCAM-1 are limited in capturing endothelial dysfunction in SA-AKI and were underrepresented or non-discriminative in sub-phenotyping efforts." (PMID 40892345, 2025). "These associations were at least as strong as with the well-validated malaria severity biomarker angiopoietin-2, and, in the case of lactate, AST, creatinine, and endothelial dysfunction, were independent of angiopoietin-2." (PMID 29872039, 2018).
breast carcinoma (51 papers, 2006 to 2026). "Based on the research results, the authors concluded that the T-T-C-A-T ANGPT2 haplotype significantly increased the risk of breast cancer development by almost 1.39 times." (PMID 40115011, 2025). "Hu and colleagues examined the effect of ANGPT2 variants on susceptibility to developing breast cancer in a Chinese Han population." (PMID 40115011, 2025). "In concordance with our findings, high ANGPT2 gene expression was associated with reduced disease-free survival and OS in patients with breast cancer." (PMID 39302921, 2024). "Coincidentally, a previous research reported that a significant positive association existed between ANGPT2 and lymph node metastasis in breast cancer." (PMID 31892982, 2020). "Over the years, many potential biomarkers have been revealed to be of diagnostic value in breast cancer, such as serum angiopoietin-2, annexin A1, and miR-22." (PMID 28523467, 2017). "An increasing body of evidence has shown that ANGPT2 is associated with tumor angiogenesis and progression in liver cancer, lung cancer, pancreatic cancer, and breast cancer." (PMID 28977900, 2017). "A more recent experimental breast cancer study linked low pericyte coverage to increased pro-metastatic Angiopoietin-2 signaling." (PMID 27248825, 2016). "Based on current findings, further studies are mandatory to verify the effect of angiopoietin-2 signaling manipulation on late recurrence prevention in women with breast cancer, particularly those under risk of estrogen deficiency." (PMID 27353038, 2016). "We also observed a tendency to decreased angiopoietin-2 levels in hormone receptor positive patients underlining a relative antiangiogenic status in hormone-receptor positive breast cancer patients." (PMID 16450002, 2006). "In this study, the ANGPT2 rs1823375 polymorphism appeared to be protective against clinically staged breast cancer and also lymph node disease, while the T-T-C-A-T ANGPT2 haplotype appeared to significantly increase the risk for developing a malignant breast neoplasm." (PMID 36008514, 2022). "Our previous work found nonsynonymous ANGPT2 gene polymorphisms in lung and colorectal cancers, which suggests that ANGPT2 SNPs might also be associated with a risk for breast cancer." (PMID 36008514, 2022). "Furthermore, co-expression analysis by cBioPortal showed that BGN was positively associated with PECAM1 and ANGPT2 expression in human breast cancers." (PMID 33966638, 2021). "Angiopoietin-2 (ANGPT2) may be the switch underling ER+ breast cancer relapse after estrogen depletion." (PMID 27353038, 2016). "Furthermore, BGN was positively associated with ANGPT2 expression in human breast cancers." (PMID 33966638, 2021). "For example, shERα cells have been observed to markedly diminish the expression of angiogenic molecular markers, including vascular endothelial growth factor A (VEGF-A) and angiopoietin-2 (Ang-2), in breast cancer cells." (PMID 39194700, 2024). "In cancer, Twist1 promotes angiogenesis, and it has been reported that Twist1 overexpression correlates with an increased expression of the vascular endothelial growth factor (VEGF) and angiopoietin-2 (Ang-2) genes in breast cancer cells." (PMID 38473317, 2024). "In fact, research in breast cancer has demonstrated that angiopoietin-2 can stimulate tumor migration and invasion through Tie-2 independent signaling." (PMID 39511039, 2024). "Previous studies have revealed that ANGPT2 expression is elevated in various tumors, such as lung cancer, breast cancer, and gastric cancer." (PMID 36907878, 2023). "In breast cancer clinical samples and cell lines, promoter hypermethylation of miR-145 and direct targeting of the angiopoietin 2 (AngpT2) gene have been found." (PMID 37298314, 2023). "Accordingly, ANGPT2 mRNA levels and survival rates in women with breast cancer deserve more investigation in future clinical trials." (PMID 36008514, 2022).
breast carcinoma (continued). "Consistent with this study, many studies have shown that ANGPT2 expression is significantly upregulated in breast cancer, pancreatic cancer, glioma, GC, colon cancer, liver cancer, melanoma, and other tumors." (PMID 36172371, 2022). "By using orthotopic and spontaneous models of breast cancer, the combination of Angiopoietin-2 (Ang2) and VEGF inhibition normalized tumor blood vessels and activated infiltrating CD8+ T cells." (PMID 34771575, 2021). "Pearson’s correlation coefficients showed that Biglycan mRNA expression was positively correlated with both PECAM1(Spearman’s correlation = 0.45) and ANGPT2 (Spearman’s correlation = 0.4) levels in human breast cancers." (PMID 33966638, 2021). "It is worth noting that transcriptome profiling of metastatic canine mammary carcinomas shows the significant downregulation of ANGPT2 and ANGPTL1-4 compared to normal mammary glands." (PMID 34685578, 2021). "ANGPT1 and ANGPT2 belong to the angiopoietin family, which play a central role in angiogenesis and are highly expressed in a variety of tumors such as GC, breast cancer and lung cancer." (PMID 33794777, 2021). "Doxorubicin (1 μM) was found to significantly stimulate the expression of PLG (plasminogen, downregulated by Twist1 inhibitors; ANGPT2 (involved in breast cancer metastasis in brain); IGF-1 (a stimulator of TWIST1) and GLI1 (activated upon TWIST1 activation)." (PMID 31331001, 2019). "More marked anti-angiogenic effects are observed when VEGF-A and angiopoietin-2 (ANGPT2) are neutralized concomitantly in the mammary tumors." (PMID 29766399, 2018). "To establish a relationship between miR-145 and ANGPT2, we measured the plasma levels of miR-145 and ANGPT2 in breast cancer patients." (PMID 28977900, 2017). "As circulating miRNAs are informative biomarkers for cancer diagnosis and prognosis, we measured circulating miR-145 and ANGPT2 levels in both breast cancer patients and healthy controls." (PMID 28977900, 2017). "Next, we found that while ANGPT2 is expressed in at a lower level normal breast epithelium, than it is in breast cancer tissues." (PMID 28977900, 2017). "In conclusion, the present study shows that the reduced expression of miR-145 in breast cancer is due to DNA methylation, and miR-145 represses cell migration and invasion by targeting ANGPT2 both in vivo and in vitro." (PMID 28977900, 2017). "The levels of miR-145 were decreased and ANGPT2 levels were increased in breast cancer patients compared with healthy controls." (PMID 28977900, 2017). "We observed a statistically significant inversed correlation between miR-145 and ANGPT2 in breast cancer samples." (PMID 28977900, 2017). "When those findings combined, it is likely that inactivation of angiopoietin-2 signaling would effectively prevent the metastatic recurrence of breast cancer, particularly of ER+ subtype." (PMID 27353038, 2016). "In our previous study, the role of angiopoietin 2 in BRCA1/2-related breast cancer angiogenesis has been highlighted." (PMID 25333258, 2015). "Anti-angiogenesis therapies have been widely studied, although the association between angiopoietin-2 (ANGPT2) single nucleotide polymorphisms (SNPs) and breast cancer subtypes remains unclear." (PMID 36008514, 2022). "A recent investigation attributed 18% of the familial risk of breast cancer risk to SNPs6, although any potential correlation between ANGPT2 gene polymorphisms and malignant breast neoplasms has not been explored so far." (PMID 36008514, 2022). "In breast cancer, ANGPT2 was correlated with poor prognosis." (PMID 36569220, 2022). "Similarly, the inhibition of Angpt2 markedly inhibits the progression of late-stage, metastatic mammary tumors and pancreatic insulinomas in murine tumor models." (PMID 35884919, 2022). "BGN was positively correlated with ANGPT2 expression in human breast cancers." (PMID 33966638, 2021). "Moreover, ANGPT2 expression was correlated with overall patient survival in colorectal and breast cancer." (PMID 31069961, 2019).
breast carcinoma (continued). "Furthermore, we showed that miR-145 represses migration and invasion in breast cancer cells by directly targeting the angiopoietin 2 gene (ANGPT2)." (PMID 28977900, 2017). "Based on the result that miR-145 directly targets ANGPT2 and is itself silenced by DNA methylation in breast cancer cell lines, we speculated that miRNA-mediated regulation might be involved in 5-AzaC-induced ANGPT2 repression in breast cancer." (PMID 28977900, 2017). "ANGPT2 promoted metastasis of breast cancer through SNAI1 induction and E-cadherin inhibition." (PMID 27323831, 2016). "Therefore, it will be valuable to compare systemic and local angiopoietin-2 levels in pre- and postmenopausal women of breast cancer." (PMID 27353038, 2016). "Angiopoietin-2 overexpression in breast cancer is known to correlate with poor patient survival." (PMID 27353038, 2016). "Interestingly, by comparing SUM149PT and MCF-7 transfected breast cancer cells, a reduction of pro-angiogenic VEGFA and ANGPT2 mRNA level was observed only in BRCA1 deficient cells transfected by hsa-miR-573 mimic." (PMID 25333258, 2015). "Increased ANGPT2 expression correlates with increased Gleason Score as well as with more invasive potential in other cancer types, such as disease progression of metastatic melanoma, metastasis to the lymph node of breast cancer, and with worse prognosis and poor survival in lung cancer patients." (PMID 35513564, 2022). "An American study that evaluated genetic associations between 17 candidate genes, including Angpt2, and the development of lymphedema following treatment for breast cancer concluded that Ang2 rs1823375 has no significant involvement in lymphangiogenesis or angiogenesis." (PMID 31929743, 2020). "In the case of breast cancer, VEGF also activates endothelial cells that increase the secretion of angiopoietin-2 (Ang-2), one of the molecules involved in the initial step of the metastasis process." (PMID 39780275, 2025). "The mRNA expression levels for eight pro-angiogenic genes [VEGFA, HGF, FGF1, FGF2, ANGPT1, ANGPT2, PDGFA, and PDGFB] were obtained from the METABRIC (Molecular Taxonomy of Breast Cancer International Consortium) dataset available at cBioPortal public domain." (PMID 39302921, 2024). "A study on an experimental breast cancer model showed that the combined inhibition of VEGF and ANGPT2 significantly reduced the number of brain metastatic lesions and their permeability." (PMID 39302921, 2024). "It is also reported that compared with the individual inhibition of Angpt2 and VEGF, their co-inhibition reduces lesion permeability and brain metastases by greater extents in experimental breast cancer metastasis." (PMID 35884919, 2022). "In breast cancer, brain microvascular endothelial cells (BMEC) overexpress angiopoietin-2, which can alter the structure of tight junction protein ZO-1 and claudin-5, attenuating the integrity of blood-brain barrier." (PMID 33688508, 2021). "In breast cancer, non‐small cell lung cancer and acute myeloid leukaemia, the expression of VEGFA and Angpt2 increased simultaneously, which promoted tumour growth." (PMID 33987885, 2021). "Neuropeptide substance P secreted by breast cancer cells can activate BMEC to produce TNF-α and angiopoietin-2 and increase blood-brain barrier permeability." (PMID 33688508, 2021). "Additional factors expressed by human breast cancer cells, such as PTH-rP and angiopoietin-2, promote tumor cell adhesiveness to fibronectin and tumor cell motility and invasion through the specific upregulation of ITGA5." (PMID 33420367, 2021). "Angiopoietin 2 (ANGPT2) involved in blood-brain barrier disruption and breast cancer metastasis in brain." (PMID 31331001, 2019). "Abnormal levels of ANGPT1 and Angiopoietin 2 (ANGPT2), together with their receptor, have been observed in prostate and breast cancer." (PMID 26044849, 2015).
breast carcinoma (continued). "Cell numbers were tested for correlation with serum levels of angiopoietin-2, erythropoietin, endostatin, endoglin, VEGF and sVCAM-1 as well as clinical and pathological features of breast cancer disease." (PMID 16450002, 2006). "In a mouse model of breast cancer with tumor-bearing mice, knockout of biglycan in the stroma inhibited metastasis to the lung, impaired tumor angiogenesis and normalized tumor vasculature by repressing TNF-α and angiopoietin 2 (ANGPT2) signaling." (PMID 34917515, 2021). "As a precursor of effective angiopoietin-2, such protein is a potential biomarker in brain cancer, breast cancer, multiple myeloma, and pancreatic cancer, but not esophageal cancer and normal controls, together with ANGPT2." (PMID 31850330, 2019). "Furthermore, BRCA1/2-related breast cancers also presented a higher percentage of VEGFA, HIF1A, FAK and ANGPT2 gene overexpression compared to the BRCAX breast tumour group (VEGFA: 62% vs 9%, p=0.04; HIF1A: 62% vs 0%, p=0.004; FAK: 62% vs 18%, p=0.073; ANGPT2: 50% vs 45%, p= 1.00)." (PMID 25333258, 2015). "This was in contrast with the expression of known HIF target genes involved in breast cancer metastasis not included in the hypoxia signatures (LOX, LOXL2, LOXL4, CCL2, L1CAM, ANGPT1, and ANGPT2), whose expression showed a positive correlation with the signatures." (PMID 29540773, 2018).